USP22 (ubiquitin specific peptidase 22)
Diseases named in the same sentence as USP22 in open-access papers (continued):
Sharing a sentence is not in itself a finding about the gene and the disease.
melanoma (continued). "Ubiquitin‐specific protease 22 (USP22) stabilizes SIRT1 and activates the PI3K/Akt/mTOR pathway through enhancing SIRT1‐mediated PTEN deacetylation, thereby promoting melanoma metastasis both in vitro and in vivo." (PMID 39135915, 2024). "The mechanism of immune therapeutic response dependent on USP22 involves STAT1 stabilization via deubiquitination and promotes the FN-JAK1-STAT1 signal, which is a pathway involved in immune therapy resistance in melanoma." (PMID 35884430, 2022). "In the initial screening of melanoma samples, five genes (USP10, USP11, USP22, USP48 and COPS5) were significantly overexpressed, compared with benign nevi." (PMID 21283576, 2011). "Consistently, protein but not mRNA levels of SIRT2, USP22, and PD- L1 positively correlate in human bladder cancer and melanoma." (PMID 42228402, 2026). "Consistently, another RNA-seq dataset from patients with advanced melanoma treated with ipilimumab followed by nivolumab revealed an increase in USP22 transcripts in nonresponders compared with responders, which were inversely correlated with B2M transcript levels." (PMID 41252204, 2025). "We found that USP22 deficiency only enhances the vulnerability of melanoma to ferroptosis inducer RSL3 and has no sensitizing effect on other antimelanoma drugs or cell death inducers, suggesting that USP22 has a specific sensitization effect on melanoma ferroptosis." (PMID 39135915, 2024). "In vivo assays further suggested that topotecan has an equivalent effect to genetic silencing of USP22 in inhibiting melanoma lung metastasis, but topotecan could not further decrease lung metastasis in the absence of USP22." (PMID 39135915, 2024). "A recent study demonstrated that ubiquitin-specific peptidase 22 (USP22) interacted with and stabilized YAP, which in turn conferred resistance to the BRAF inhibitor vemurafenib and provided new therapeutic avenues to target USP22/YAP as an option for melanoma treatment." (PMID 36694209, 2023). "However, the functional impact of USP22 deubiquitylation of histone or non-histone substrate regulation has not yet been studied in the melanoma process." (PMID 35884430, 2022). "Thus, overexpression of USP22 resulted in resistance to the BRAF inhibitor vemurafenib through the stabilization of YAP and opened new therapeutic avenues for combined inhibition of USP22/YAP and BRAF as an option for melanoma treatment." (PMID 35884430, 2022). "However, USP22 inhibition could not further enhance the inhibitory effect on melanoma invasion in the presence of PI3K inhibitor (GDC‐0941), Akt inhibitor (MK‐2206), or mTOR inhibitor (CCI‐779)." (PMID 39135915, 2024).
glioma (10 papers, 2016 to 2025). A benign or malignant brain and spinal cord tumor that arises from glial cells (astrocytes, oligodendrocytes, ependymal cells). "The upregulation of USP22 was also reported to be associated with a poor prognosis in papillary thyroid carcinoma and glioma." (PMID 34660907, 2020). "The GSK3β-dependent phosphorylation of LSD1 contributes to the stability of the LSD1 protein, and phosphorylated LSD1 enhances its binding affinity with ubiquitin-specific protease 22 (USP22) in glioma stem cells, thereby promoting tumorigenicity." (PMID 39595520, 2024). "Under hypoxic conditions, USP22 stabilizes BMI1 to induce CSC formation for cancer progression in glioma models." (PMID 34660907, 2020). "Over the years, upregulation of USP22 has been validated in several cancers such as breast, colorectal, pancreatic, lung, ovarian, bladder, lymphoma, glioma, mesothelioma, neuroblastoma, etc.." (PMID 34660907, 2020). "As a possible translational application of our results, we recall the role of the “cancer signature gene” Usp22, an orthologue of Ubp8p, in aggressive tumors such as kidney tumors and glioma." (PMID 32788380, 2020). "It has been reported that USP22 silencing induced apoptosis of bladder, colorectal, and glioma cancer cells." (PMID 27145278, 2016). "Both USP22 and Bmi‐1 regulate a series of genes involved in glioma stemness." (PMID 39791545, 2025). "The role of USP22 and BMI1 in glioma associated stem cells has also been reported." (PMID 34660907, 2020).
osteosarcoma (9 papers, 2022 to 2025). A usually aggressive malignant bone-forming mesenchymal neoplasm, predominantly affecting adolescents and young adults. "Studies have demonstrated that reprogramming of glucose metabolism is a major factor in the development and progression of osteosarcoma, and that USP22 is strongly associated with the metabolism of glucose in osteosarcoma." (PMID 39661501, 2024). "Kaplan-Meier survival analysis using the GSE21257 dataset revealed that high USP22 expression was associated with poor prognosis of osteosarcoma patients (p < 0.05)." (PMID 38784391, 2024). "Based on bioinformatics analysis, USP22 is highly expressed in osteosarcoma and associated with poor survival of patients." (PMID 38784391, 2024). "Therefore, glycolysis/gluconeogenesis was considered a key signaling pathway associated with USP22 in osteosarcoma." (PMID 38784391, 2024). "Moreover, survival analysis combined with clinical data revealed, for the first time, high USP22 expression was closely associated with poor prognosis of osteosarcoma patients." (PMID 38784391, 2024). "The glycolysis precise molecular process underlying USP22 involvement in osteosarcoma remains unclear despite the fact that the protein's significance in osteosarcoma has been partially revealed more research is necessary to determine this." (PMID 39661501, 2024). "USP22 also showed potential as a diagnostic marker for osteosarcoma." (PMID 38784391, 2024). "Here, we will utilize bioinformatics approaches to explore the function of USP22 in osteosarcoma initiation, progression and prognosis, identify the potential mechanisms, and further validate experimentally the effects of USP22 on osteosarcoma cell growth and underlying mechanisms." (PMID 38784391, 2024). "USP22 expression was increased in osteosarcoma tissues and linked to osteosarcoma progression." (PMID 35692754, 2022). "We found that USP22 was highly expressed in osteosarcoma tissues and correlated with poor prognosis in osteosarcoma patients." (PMID 38784391, 2024). "In vitro and in vivo studies have demonstrated that USP22 stimulates aerobic glycolysis in osteosarcoma cells, thereby promoting osteosarcoma progression." (PMID 39661501, 2024). "Overall, these results indicate that β‐catenin in osteosarcoma cells is regulated by USP22 via the ubiquitin proteasome pathway." (PMID 39661501, 2024). "This study aims to investigate the function and potential mechanism of USP22 in osteosarcoma using bioinformatics analysis combined with experimental validation." (PMID 38784391, 2024). "In this study, we utilized multiple bioinformatics tools combined with in vitro experiments to investigate the role and mechanisms of USP22 in osteosarcoma." (PMID 38784391, 2024). "Specifically, we examined the role of USP22 expression in glycolysis and the proliferation of osteosarcoma cells using molecular techniques." (PMID 39661501, 2024). "The molecular mechanisms by which USP22 promotes osteosarcoma involve multiple signaling pathways, including glycolysis, oxidative phosphorylation, Spliceosome, Thermogenesis, and Cell cycle." (PMID 38784391, 2024). "Overall, these results indicate that USP22 regulates HK2‐mediated glycolysis in osteosarcoma cells via β‐catenin." (PMID 39661501, 2024). "USP22 promotes the progression of osteosarcoma by enhancing glycolysis and cell proliferation, both in vivo and in vitro." (PMID 39661501, 2024). "Overexpression of miR-140 inhibits osteosarcoma cell proliferation, migration, and invasion and promotes apoptosis by downregulating USP22 expression." (PMID 39062505, 2024). "Firstly, by comparing USP22 expression between osteosarcoma and adjacent tissues, we found USP22 was markedly upregulated in osteosarcoma, consistent with previous reports." (PMID 38784391, 2024). "Overall, these results indicate that USP22 promotes the proliferation of osteosarcoma cells both in vivo and in vitro." (PMID 39661501, 2024).
osteosarcoma (continued). "In the present study, we examined the expression and role of USP22 in osteosarcoma in vivo and in vitro." (PMID 39661501, 2024). "To validate the accuracy of bioinformatics analyses, we downregulated USP22 expression in osteosarcoma cell line Sao-2 using siRNA and assessed its effect on cell proliferation, migration, invasion, apoptosis, and regulation of key signaling pathways." (PMID 38784391, 2024). "We first integrated transcriptomic datasets and clinical information of osteosarcoma from GEO and TCGA databases to assess the expression and prognostic value of USP22 in osteosarcoma." (PMID 38784391, 2024). "The results of Western blot analysis and quantitative reverse transcription polymerase chain reaction (qRT‐PCR) showed that the expression of USP22 in osteosarcoma tissues was significantly higher than that in adjacent healthy tissues." (PMID 39661501, 2024). "Kaplan-Meier survival analysis showed that high USP22 expression correlated with poor prognosis of osteosarcoma patients (p < 0.05)." (PMID 38784391, 2024). "To investigate the role of USP22 in osteosarcoma, we compared the expression levels of USP22 in osteosarcoma tissue and neighbouring tissues and found that USP22 mRNA expression was significantly higher in osteosarcoma tissue than in neighbouring tissues." (PMID 39661501, 2024). "USP22 influences osteosarcoma cell proliferation, invasion, and migration by regulating the PI3K/Akt signaling pathway and the expression of EMT-related markers." (PMID 39062505, 2024). "CCK-8 data showed that USP22 overexpression accelerated viability of osteosarcoma cells, which was rescued by miR-485-5p upregulation." (PMID 35692754, 2022). "In our study, we found that miR-485-5p inhibited the expression of USP22 in osteosarcoma cells, leading to suppression of viability and motility of osteosarcoma cells." (PMID 35692754, 2022). "Strikingly, linc00265 exerted its oncogenic function via regulating miR-485-5p and USP22 in osteosarcoma." (PMID 35692754, 2022). "Our results suggested that linc00265 upregulation increased the expression of USP22 at mRNA and protein levels, and linc00265 downregulation attenuated the USP22 expression levels in osteosarcoma cells." (PMID 35692754, 2022). "Western blotting data further validated that miR-485-5p overexpression reduced the expression of USP22 protein, whereas miR-485-5p downregulation increased the USP22 protein levels in osteosarcoma cells." (PMID 35692754, 2022). "RT-PCR was performed to examine the expression of USP22 mRNA in osteosarcoma cells after miR-485-5p mimic treatment or inhibitor exposure." (PMID 35692754, 2022). "Here, we reported that linc00265 facilitated osteosarcoma progression via targeting miR-485-5p/USP22 axis." (PMID 35692754, 2022). "Furthermore, ALKBH5-mediated m6A deficiency increases the expression of USP22 and RNF40 in osteosarcomas, promoting osteosarcoma cell growth and proliferation." (PMID 40001461, 2025). "Additionally, USP22 knockdown decreased the proliferation and glycolytic rate of the osteosarcoma cell line 143B." (PMID 39661501, 2024). "However, the effects of USP22 knockdown were partially counteracted by HK2 overexpression, suggesting that USP22 promotes glycolysis and cell proliferation in osteosarcoma by upregulating the expression of HK2." (PMID 39661501, 2024). "Through screening for co-expressed genes with USP22 and functional enrichment analysis, we found that the pro-osteosarcoma mechanisms of USP22 may involve the glycolysis/gluconeogenesis pathway." (PMID 38784391, 2024). "This implies USP22 may participate in the development and prognosis of osteosarcoma through interactions with these co-expressed genes." (PMID 38784391, 2024). "Therefore, this study aimed to investigate the expression, role and potential mechanism of USP22 in osteosarcoma." (PMID 39661501, 2024).
osteosarcoma (continued). "USP22 could influence Sao-2 cell proliferation, apoptosis, migration, and invasion by regulating the glycolysis pathway, thereby promoting osteosarcoma progression." (PMID 38784391, 2024). "Downregulation of USP22 can inhibit the glycolysis and growth of osteosarcoma cells." (PMID 38784391, 2024). "In addition, the expression of USP22 promotes the proliferation of osteosarcoma cells in a glycolytic dependent manner both in vitro and in vivo, while the knockout of USP22 is the opposite." (PMID 39661501, 2024). "In summary, our study demonstrates the oncogenic role of USP22 in osteosarcoma." (PMID 38784391, 2024). "To confirm our hypothesis, we examined HK2 protein and mRNA expression in osteosarcoma cells following USP22 knockdown and overexpression." (PMID 39661501, 2024). "In this study, USP22 was highly expressed in osteosarcoma tissue samples and cell lines." (PMID 39661501, 2024). "Additionally, we assessed the ECAR in osteosarcoma cells to determine the impact of USP22 on glycolysis." (PMID 39661501, 2024). "The genes co-expressed with USP22 may have a close regulatory relationship with USP22 in the occurrence, development, and prognosis of osteosarcoma." (PMID 38784391, 2024). "USP22 plays a critical role in the occurrence, development, and prognosis of osteosarcoma." (PMID 38784391, 2024). "We found that USP22 knockdown could inhibit the glycolytic pathway in osteosarcoma cells, suppress cell proliferation, migration and invasion, and promote cancer cell apoptosis." (PMID 38784391, 2024). "Importantly, linc00265 exerts its oncogenic function by regulating the expression levels of miR-485-5p and USP22 in osteosarcoma." (PMID 39062505, 2024). "Furthermore, we examined the effect of USP22 on osteosarcoma cell apoptosis using flow cytometry and found that USP22 knockdown significantly increased 143B cell apoptosis compared with that in the shNC treatment group." (PMID 39661501, 2024). "Collectively, these results suggest that USP22 promotes aerobic glycolysis in osteosarcoma cells." (PMID 39661501, 2024). "Moreover, immunohistochemical (IHC) indicated that osteosarcoma tissues had considerably elevated USP22 levels." (PMID 39661501, 2024). "Collectively, these results suggest that HK2 mediates glycolysis in osteosarcoma cells via USP22." (PMID 39661501, 2024). "To verify our hypothesis, we examined whether endogenous USP22 can directly interact with β‐catenin in osteosarcoma cells and found that there was a considerable interaction between USP22 and β‐catenin." (PMID 39661501, 2024). "Given that USP22 is positively associated with HK2, we speculate that USP22 modulates glycolysis in osteosarcoma cells by regulating the expression of HK2." (PMID 39661501, 2024). "Furthermore, qRT‐PCR and western blot analyses confirmed that USP22 expression was significantly higher in osteosarcoma cell lines (143B, HOS, MG‐63 and U2‐OS) than in the normal bone cell line hfoBI‐19." (PMID 39661501, 2024). "Furthermore, USP22-induced cell migration and invasion were abolished by miR-485-5p overexpression in osteosarcoma cells." (PMID 35692754, 2022). "Notably, linc00265 sponged miR-485-5p and increased the expression of USP22, one target of miR-485-5p, in osteosarcoma cells." (PMID 35692754, 2022). "Moreover, linc00265-induced colony formation was rescued by inhibition of USP22 in osteosarcoma cells." (PMID 35692754, 2022). "We also confirmed that USP22 enhanced viability and motility of osteosarcoma cells." (PMID 35692754, 2022). "Our study demonstrated that linc00265 promoted cell viability, migration and invasion via targeting miR-485-5p/USP22 axis in osteosarcoma, suggesting that linc00265 might be a useful target for osteosarcoma therapy." (PMID 35692754, 2022). "USP22 and miR-485-5p could have several downstream targets, which need to be further explored in osteosarcoma cells." (PMID 35692754, 2022).
osteosarcoma (continued). "Lastly, we examined whether miR-485 and USP22 were involved in linc00265-mediated oncogenic function in osteosarcoma cells." (PMID 35692754, 2022). "The detailed mechanism of USP22-mediated osteosarcoma is still elusive." (PMID 35692754, 2022). "Therefore, targeting the USP22/β‐catenin/HK2 axis may be an effective strategy for osteosarcoma treatment." (PMID 39661501, 2024). "Presently, it is uncertain whether USP22 plays a role in β‐catenin ubiquitination in osteosarcoma." (PMID 39661501, 2024). "However, the precise function and molecular mechanism of USP22 in osteosarcoma remain unexplored." (PMID 39661501, 2024). "Based on these results, it could be concluded that USP22 regulates β‐catenin in osteosarcoma cells." (PMID 39661501, 2024). "Additionally, USP22‐knockdown osteosarcoma cells were treated with cycloheximide." (PMID 39661501, 2024). "However, the role and mechanism of USP22 in osteosarcoma is not fully understood." (PMID 38784391, 2024). "However, the role and mechanism of USP22 in osteosarcoma remains rarely reported." (PMID 38784391, 2024). "Therefore, we speculated that USP22 may stabilise β‐catenin in osteosarcoma cells and promote its entry into the nucleus." (PMID 39661501, 2024). "Therefore, we speculated that the effect of USP22 on glycolysis in osteosarcoma cells might be related to HK2." (PMID 39661501, 2024). "Furthermore, current research indicates that USP22 facilitates the glycolysis of osteosarcoma." (PMID 39661501, 2024). "Therefore, the miR-140/USP22/LSD1 axis regulates osteosarcoma tumor progression." (PMID 39062505, 2024). "Additionally, HK2 mediates USP22‐induced regulation of glycolysis in osteosarcoma cells." (PMID 39661501, 2024). "Notably, RNA demethylase ALKB Homolog 5 (ALKBH5)-mediated m6A deficiency in osteosarcoma leads to increased expression of USP22 and RNF40, suppressing H2A ubiquitination and promoting gene expression related to replication and DNA repair, driving osteosarcoma progression." (PMID 39048965, 2024). "However, few studies demonstrate the inhibitory effects of USP22 on osteosarcoma cells and the specific mechanisms remain unclear." (PMID 38784391, 2024). "Therefore, to investigate the molecular mechanism by which USP22 activates HK2 in osteosarcoma cells, we verified whether endogenous USP22 and HK2 directly bind to 143B cells." (PMID 39661501, 2024). "Moreover, inhibition of USP22 reduced osteosarcoma tumor growth and metastasis in mice." (PMID 35692754, 2022). "Furthermore, we identified that USP22 is a direct target of miR-485-5p in osteosarcoma cells." (PMID 35692754, 2022). "qRT‐PCR and western blot analysis showed that USP22 and HK2 were highly expressed in osteosarcoma tissues and were positively correlated." (PMID 39661501, 2024). "Mechanistically, USP22 regulates HK2 by deubiquitination and stabilising the expression of β‐catenin, thereby controlling glycolysis in osteosarcoma cells." (PMID 39661501, 2024). "USP22 inhibits LSD1 ubiquitination and degradation through deubiquitination, thereby promoting osteosarcoma progression." (PMID 39062505, 2024). "Another study demonstrated the low expression of miR-140 and p21, and high expression of USP22 and LSD1 in osteosarcoma cells." (PMID 39062505, 2024). "To elucidate the role of USP22 on osteosarcoma cell proliferation, we generated 143‐B cells stably expressing USP22 shRNA and U2OS cells overexpressing USP22." (PMID 39661501, 2024). "Therefore, USP22 may be a potential therapeutic target for the treatment of osteosarcoma." (PMID 38784391, 2024). "However, it is still unknown how precisely USP22 works in osteosarcoma." (PMID 39661501, 2024). "In contrast, USP22 overexpression significantly increased the protein levels of HK2 and β‐catenin and promoted the proliferation and glycolytic rate of osteosarcoma cells." (PMID 39661501, 2024).